LRRTM3 (leucine rich repeat transmembrane neuronal 3)
Description:
Exhibits a limited synaptogenic activity in vitro, restricted to excitatory presynaptic differentiation (By similarity). May play a role in the development and maintenance of the vertebrate nervous system.
Tractability: Small molecule: it belongs to a druggable protein family. Antibody: UniProt places it where antibodies can reach, with medium confidence; UniProt predicts a signal peptide or a membrane-spanning region; its Gene Ontology location is reachable by antibodies, with medium confidence. PROTAC: its protein half-life has been measured.
Gene: Protein-coding gene on chromosome 10 (66,926,036 to 67,101,551, forward strand). Ensembl gene ENSG00000198739.
Subcellular location: Cell membrane; Postsynaptic cell membrane
Pathways (Reactome):
Neuronal System: Neurexins and neuroligins
Gene Ontology:
Molecular function: signaling receptor activity
Biological process: positive regulation of amyloid-beta formation; regulation of presynapse assembly; positive regulation of synapse assembly
Cellular component: glutamatergic synapse; plasma membrane; postsynaptic density membrane; postsynaptic membrane; synapse
Genetic constraint (gnomAD): Loss-of-function variants: 24 observed, 46.79 expected, observed/expected ratio (o/e) 0.51, 90% interval 0.37 to 0.72. The upper end of that interval is the gene's LOEUF score, 0.72, which puts it in group 2 of 6, group 1 being the genes least tolerant of losing a copy. Missense variants: 587 observed, 746.33 expected, observed/expected ratio (o/e) 0.79, 90% interval 0.73 to 0.84. Synonymous variants: 277 observed, 297.87 expected, observed/expected ratio (o/e) 0.93, 90% interval 0.84 to 1.03.
Homologues: Orthologues: chimpanzee LRRTM3 (100% identical), macaque LRRTM3 (100% identical), rabbit LRRTM3 (99% identical), guinea pig LRRTM3 (99% identical), dog LRRTM3 (99% identical), mouse Lrrtm3 (98% identical), rat Lrrtm3 (97% identical), pig LRRTM3 (89% identical), tropical clawed frog lrrtm3 (67% identical). Paralogues in human: LRRTM4 (59% identical), LRRTM1 (40% identical), FLRT2 (20% identical), FLRT3 (20% identical), LRRC4C (19% identical), FLRT1 (19% identical), LRRC15 (18% identical), LRRC4B (18% identical), RTN4R (17% identical), LRRC4 (17% identical), NYX (17% identical), RTN4RL2 (17% identical), and 10 more.
Diseases named in the same sentence as LRRTM3 in open-access papers:
LRRTM3 is named in the same sentence as 10 diseases in open-access papers, as found by Europe PMC text mining. Sharing a sentence is not in itself a finding about the gene and the disease. The quoted sentences say what the papers report.
autism (3 papers, 2013 to 2022). Persistent deficits in social interaction and communication and interaction as well as a markedly restricted repertoire of activity and interest as well as repetitive patterns of behavior. "LRRTM3, an evolutionarily conserved member of a synaptic protein family was also detected as a risk gene in autism, raising the possibility of a potential role of this gene in the neurodevelopment-neurodegeneration axis." (PMID 23750206, 2013). "Moreover, a similar sequence of events to this was observed with respect to the convergent transcription of the overlapping LRRTM3 and CTNNA3 genes associated with autism." (PMID 34440463, 2021).
Alzheimer disease (2 papers, 2013 to 2014). A progressive, neurodegenerative disease characterized by loss of function and death of nerve cells in several areas of the brain leading to loss of cognitive function such as memory and language. "LRRTM3 is a nested gene within α-T catenin (CTNNA3) and resides at the linkage peak for late-onset Alzheimer’s disease (LOAD) risk and plasma amyloid β (Aβ) levels." (PMID 23750206, 2013).
neuroblastoma (2 papers, 2013 to 2020). Neuroblastoma (NB) is the most common solid, extracranial childhood tumor. "The siRNA-based LRRTM3 knockdown in SH-SY5Y human neuroblastoma cells reduces Aβ secretion and the production of the intracellular C-terminal fragments (CTFs) by β-secretase (βCTF), suggesting that LRRTM3 positively modulates BACE1 processing of APP." (PMID 32982693, 2020). "Human neuroblastoma SH-SY5Y cells with stable overexpression of wild type APP (SH-SY5Y-APP695wt) were transfected with either anti-LRRTM3 siRNA (si-LRRTM3, SASI_Hs01_00163676, Sigma) or control (si-control, SIC001 MISSION Universal Negative Control#1, Sigma)." (PMID 23750206, 2013).
age (1 paper, 2024). A temporal measurement of the time period elapsed since an identifiable point in the life cycle of an organism. "Downregulation of Ntng1 and Lrrtm3 might affect hippocampal glutamatergic synapses and contribute to age‐related cognitive impairment, which is consistent with our functional analysis results." (PMID 39468399, 2024).
infertility disorder (1 paper, 2025). Inability to conceive for at least one year after trying and having unprotected sex. "A recent study reported the region of OAR25 close to the genes CTNNA3 and LRRTM3 as being prone to escape reprogramming and a potential candidate for transgenerational epigenetic inheritance, suggesting a potential genetic overlap between brain and infertility disorders." (PMID 40678382, 2025).
prostate carcinoma (1 paper, 2021). A carcinoma that arises from epithelial cells of the prostate gland. "Furthermore, LRRTM3 has no published connection to AR or prostate cancer." (PMID 33513133, 2021).
LRRTM3 also shares sentences with these, for which no sentence is quoted: brain disorder (1 paper); Cognitive impairment (1); schizophrenia (1); Tourette syndrome (1).